CAT (catalase)
Diseases named in the same sentence as CAT in open-access papers (continued):
Sharing a sentence is not in itself a finding about the gene and the disease.
melanoma (continued). "According to our analysis, 66% of the isoforms presented differential expression on melanoma progression: NOS2, SOD1, NOX4, PRX3, PXDN and GPX1 are increased during melanoma progression, while CAT, GPX3, TXNIP, and PRX2 are decreased." (PMID 35326089, 2022). "When melanoma cells were injected in mice and the animals were treated with PEG-catalase intravenously, almost a complete suppression of the growth of metastatic tumor in the lung was observed." (PMID 35326089, 2022). "It has been demonstrated that melanoma cells are resistant to oxidative stress by maintaining elevated GSH, SOD, CAT and GPX levels." (PMID 35326089, 2022). "In this sense, despite some redox imbalance controversy of catalase, the use of PEG-catalase seems a promising therapy for melanoma." (PMID 35326089, 2022). "In primary melanoma, Mn-SOD2, Cu/Zn-SOD1, and CAT expression are elevated compared with normal skin and melanocytic nevi." (PMID 34777692, 2021). "The upregulation of CAT, SODs, GPx and glutamate-l-cysteine ligase catalytic subunit (GCLC) in human melanoma biopsies and a large set of melanoma cell lines was demonstrated in a systematic review." (PMID 33091721, 2020). "Considering the increased levels of ROS observed in A375 melanoma cells as compared to PIG-1 melanocytes, we generated a model of catalase overexpression with A375 cells." (PMID 22970236, 2012). "Oxidative damage and lipid peroxidation is recovered by treatment with MQ-EO through the upregulation of glutathione (GSH) levels or anti-oxidants, such as superoxide dismutase (SOD), glutathione peroxidase (GPx), and catalase (CAT), in α-MSH-stimulated B16 melanoma." (PMID 38791435, 2024). "However, due to the rescue with PEG—catalase and being aware of the glucose dependency of melanoma cells, we assumed an additional mechanism for the toxicity of CNP towards the malignant melanoma cells involving reactive oxygen species." (PMID 38512909, 2024). "In the presence of sulindac, the catalase activity decreased proportionally to the concentration in melanotic melanoma cells but no changes were observed for amelanotic cells." (PMID 37195561, 2023). "The three-dimensional (3D) reconstructed RhB FL imaging of MN patch (loaded with CCPCA-RhB NPs)-treated skin of A375 melanoma tumors also identified several micropores in the skin, confirming the skin permeability of the MN-CCPCA patch to deliver both 5-ALA and CAT locally at the target site." (PMID 36266306, 2022). "However, thermal shock was found quite efficient for loading of catalase into RAW 264.7 macrophage-derived EVs, and hollow gold nanoparticles into EVs from mouse melanoma B16-F10 cell line." (PMID 32610582, 2020). "Notably, hinokitiol (1–5 μM) increased the activities of antioxidant enzymes catalase (CAT) and superoxide dismutase (SOD) from the reduction in melanoma cells." (PMID 26404213, 2015). "Novel strategies against melanoma aiming at exacerbation of ROS levels to induce DNA damage and apoptosis have been proposed in combination with inhibition of anti-oxidant enzymes (SOD, catalase and redox transcription factors)." (PMID 25296975, 2014). "We observed a high percentage of p27Kip1 positive nuclei in melanoma cells overexpressing or treated with exogenous catalase, while non-treated controls showed a cytoplasmic localization of p27Kip1." (PMID 22970236, 2012). "Moreover, ChA in C32 cells suppressed the viability of melanoma cells and the expression of genes of antioxidant enzymes superoxide dismutase (SOD1, SOD2) and glutathione peroxidase (GPX1), as well as activity of SOD, GPx, and catalase (CAT)." (PMID 37687080, 2023). "In our melanoma cellular model, non significant differences were observed in p27pT187 levels after ROS modulation, both by addition or scavenging of H2O2, which is consistent with the fact that no variations were observed on cyclin E and CDK2 levels after catalase treatment." (PMID 22970236, 2012).
Cerebral ischemia (46 papers, 2011 to 2026). Restriction of arterial blood supply to the brain associated with insufficient oxygenation to support the metabolic requirements of the tissue. "Our recent study demonstrated that galangin significantly decreased lipid peroxidation and increased catalase and glutathione peroxidase levels in the cortex and hippocampal regions affected by cerebral ischemia." (PMID 40076473, 2025). "Pretreatment with CH-SIL NPs reduced the lipid peroxidation reactions and enhanced the activities of SOD, CAT, and GPx, in cerebral ischemia/reperfusion rats." (PMID 38645495, 2024). "Isoliquiritin acts as an “activator” of superoxide dismutase and catalase enzymes to control diseases such as cancer and cerebral ischemia." (PMID 37110708, 2023). "Our preceding study reveals that a positive correlation was found between the Zn level and the antioxidant activities of SOD and CAT in the ischemic brain cortex during cerebral ischemia." (PMID 35204278, 2022). "The activities of antioxidant enzymes catalase (CAT), glutathione reductase (GR), and glutathione peroxidase (GPx) were assessed 48 h after the induction of cerebral ischemia in the plasma from mice fed with LFD, HFD-SFA, HFD-OO, or HFD-OO-ω3." (PMID 31109078, 2019). "The same study identified that fenofibrate significantly increased the activities of antioxidant enzymes superoxide dismutase and catalase in cerebral ischemia, which deactivate ROS to alleviate oxidative stress." (PMID 25705219, 2015). "Thus, in models of cerebral ischemia, catalase and superoxide dismutase (two antioxidant enzymes) and inhibition of neuronal nitric oxide synthase reduce infarct size." (PMID 36671047, 2023). "In addition to the accumulation of free radicals, deficiency of superoxide dismutase, glutathione peroxidase and catalase has also been found after cerebral ischemia." (PMID 35052650, 2022). "In cerebral ischemia, deacetylation of FoxO3a by SIRT3 causes the translocation of FoxO3a into the nucleus and enhancement of FoxO3a-dependent antioxidant protection associated with the activation of catalase and superoxide dismutase 2 (SOD2)." (PMID 35574497, 2022). "Proper CAT activity is helpful to eliminate cerebral ischemia-generated toxic hydrogen peroxide." (PMID 34679650, 2021). "In a permanent cerebral ischemic model in rats, in which the bilateral common carotid arteries are ligated, oral feeding of total flavonoid (17.5-70 mg/kg) from Scutellaria baicalensis increase SOD and catalase (CAT) activity in the hippocampus and cerebral ischemia cortex." (PMID 21740583, 2011). "Also, STC1 was found to increase the activity of SOD and CAT in the hippocampus of a cerebral ischemia/reperfusion rat model, thereby reducing oxidative stress and blood brain barrier permeability to ameliorate cerebral ischemia, which was consistent with our findings." (PMID 34194345, 2021). "Delivery of catalase to ischemic subregions and cerebral neurocytes of MCAO mice was achieved by these neutrophil-mediated nanoparticles and the therapeutic outcome of cerebral ischemia was greatly improved." (PMID 40948582, 2025). "After cerebral ischemia–reperfusion induction, both SOD and CAT levels markedly decreased in the IR group compared to the sham group." (PMID 39057078, 2024). "A study with a similar design also showed that cerebral ischemia induces an increase in MDA and a reduction in GPx, GSH, CAT, and SOD in an experimental model of brain ischemia–reperfusion injury." (PMID 38540199, 2024). "Results indicated that cerebral ischemia markedly decreased SOD, CAT, Mg, Zn, Se, and Zn/Cu ratio and increased malondialdehyde (MDA), Fe, Cu, and Pb in the ischemic brain cortex." (PMID 35204278, 2022). "Our present findings highlight that cerebral ischemia not only results in brain tissue decreases in Mg, Zn, Se, and the Zn/Cu ratio and antioxidant activity of SOD and CAT, but also increases concentrations of MDA, Fe, Cu, and Pb." (PMID 35204278, 2022).
Cerebral ischemia (continued). "During cerebral ischemia and reperfusion, the production of ROS is significantly increased, and SOD can be consumed by catalase reactions." (PMID 35242008, 2022). "Accordingly, we propose that the mechanism underlying the neuroprotective effects of quercetin on ischemic brain cortex during cerebral ischemia involve its induction of increased levels of Se, SOD, and CAT." (PMID 34684707, 2021). "An in vivo investigation utilizing a focal cerebral ischemia model found that HBOT preconditioning elevated SOD and CAT mechanisms in cerebral tissue, leading to increased survival rates, as well as ameliorated neurological function and cell damage." (PMID 32899709, 2020). "As a free radical scavenger, SOD, CAT, GSH, and GSH-Px have significant antioxidative effects in cerebral ischemia and hypoxia, and have received increasing attention." (PMID 32149332, 2020). "A study showed that p-coumaric acid pretreatment has neuroprotective effect in cerebral ischemia-reperfusion and increased levels of SOD and catalase (Sakamula and Thong-Asa, 2018 ▶)." (PMID 33299819, 2020). "Reperfusion after cerebral ischemia (R/I) in MetS rats increased MDA, TNF-α, and IL-6 levels, but it decreased the activities of the main scavenger enzymes including SOD, CAT, and GSH-Px and neuron densities in CA2 and CA3 subregions of the hippocampus." (PMID 30937145, 2019). "Oxidative stress-induced increase in Nrf2 and its targeted genes, catalase and SOD detected in the current study is analogous to observations demonstrated previously in a cerebral ischemia model." (PMID 29348410, 2018). "Cerebral ischemia led to decreases in GPx and SOD activity, as well as an increase in catalase activity." (PMID 27252774, 2016). "In this study, Rt.MCAO led to a marked reduction in hippocampal SOD, CAT, and GSH-Px levels, reflecting a compromised antioxidant defense system, which aligns with previous findings highlighting the overproduction of ROS during cerebral ischemia." (PMID 40507904, 2025). "Cerebral ischemia is known to lead to excessive production of ROS and an increase in their levels, which are regulated by endogenous antioxidant enzymes, including SOD, CAT, and GPX (glutathione peroxidases)." (PMID 37511195, 2023). "In a diabetic rat model of cerebral ischemia–reperfusion, administration of Res at a dose of 20 mg/kg effectively reduced levels of malondialdehyde (MDA), TNF-α, IL-6 and myeloperoxidase (MPO), while increasing levels of catalase (CAT), superoxide dismutase (SOD), and IL-10." (PMID 41601537, 2026). "Additionally, this investigation reveals that pretreatment with soybean isoflavones markedly lowers MDA and LDH levels in the brain tissue of rats suffering from cerebral ischemia–reperfusion injury while notably enhancing the activities of SOD, GSH-px, and CAT." (PMID 40283984, 2025). "However, no significant change of CAT was observed in MetS rats with cerebral ischemia and received the high dose of PMG." (PMID 32774678, 2020).
liver fibrosis (46 papers, 2013 to 2025). "DHZ ameliorated the TAA-mediated downregulation of catalase activity, thereby alleviating hepatic fibrosis progression." (PMID 41357857, 2025). "At the same time, curcumin can improve the levels of GSH, SOD, and CAT in liver fibrosis induced by thioacetamide and bisphenol a, and reduce MDA." (PMID 41357857, 2025). "Although the PPARα‐catalase pathway has been reported in the treatment of alcoholic liver disease, hepatic fibrosis, and skin aging, this study is the first to elucidate its role in mitigating FC‐induced oxidative stress in NAFLD through DhT treatment." (PMID 39558866, 2025). "The BDL model of liver fibrosis is reported to be associated with decreased SOD and CAT activities in the liver tissue." (PMID 37736516, 2023). "It protects the liver from volatile OH free radicals produced from hydrogen peroxide in CCl4-induced liver fibrosis rats by upregulating Nrf-2 and boosting the expression of its target gene catalase." (PMID 36985782, 2023). "Compared with normal tissues, Collagen I, α-SMA, and HIF-1α were highly overexpressed in cirrhosis tissues, and CAT expression displayed dark areas, indicating that liver fibrosis was accompanied with hypoxia and decreased CAT expression." (PMID 36797395, 2023). "Nevertheless pomegranate’s retaliation to this damage of catalase and glutathione levels is indicative of utilization of its antioxidant activity in the mechanism against hepatic fibrosis." (PMID 29872102, 2018). "Studies have suggested that antioxidants such as SOD, catalase, and estradiol significantly prevent lipid peroxidation and exacerbation of liver fibrosis." (PMID 24995353, 2014). "Notably, betaine attenuated MIF effects in myocardial tissue reducing levels of MDA, AOPP, TNF, TGF-β1, PDGF-BB and increasing SOD and catalase activity in the coexistence of liver fibrosis." (PMID 41020850, 2025). "Furthermore, SOD and CAT enzyme activities were sharply reduced in TAA-induced liver fibrosis, whereas treatment with DPx restored SOD and CAT activities in the liver of TAA-treated mice." (PMID 37324954, 2023). "A drop in hepatic SOD and CAT activities in the hepatotoxic group might explain elevated MDA.TAA created liver fibrosis in rats." (PMID 36458098, 2023). "In this study, knockout MIF−/− mice in TAA-induced liver fibrosis showed increased levels of SOD, CAT and thiols in myocardial tissue compared to wild-type mice." (PMID 41020850, 2025). "Curcumin nanoparticles can improve the bioavailability and biodistribution, which significantly decreased MDA and significantly improved CAT, SOD and GSH in thioacetamide (TAA) -stimulated hepatic fibrosis in rats." (PMID 41357857, 2025). "After inducing an experimental liver fibrosis model using CCl4, significant reductions in SOD and CAT activities (p < 0.001) were observed in comparison to the control and sham groups, as well as the PINX groups." (PMID 39007940, 2025). "TQ treatment (2, 5, and 10 mg/kg for 3 weeks, IP) modified inflammatory-induced liver fibrosis by affecting oxidant/anti-oxidant balance (reduced MDA and increased activity of SOD and CAT enzymes)." (PMID 38911247, 2024). "In LPS-treated rats, liver fibrosis and oxidant/anti-oxidant imbalance (elevated MDA and decreased CAT and SOD) were observed." (PMID 38911247, 2024). "Compared to the control group, liver fibrosis significantly increased the content or activity of SOD, GSH, CAT, and GSH-Px while significantly decreasing the activity of MDA (p < 0.001)." (PMID 39195542, 2024). "Administration of ground apricot kernel increased liver CAT and SOD activities, whereas it decreased the MDA level and liver fibrosis induced by dimethylnitrosamine in rats." (PMID 39170485, 2024). "In the current study, we explored clinical specimens obtained from cirrhosis patients and a mouse model of liver fibrosis to demonstrate upregulated HIF-1α, decreased CAT activity, and H2O2 accumulation in fibrotic regions." (PMID 36797395, 2023).
liver fibrosis (continued). "Catalase (CAT) is the major antioxidant enzyme that catalyzes H2O2 into oxygen and water, which loses its activity in different liver diseases, especially in liver fibrosis." (PMID 36797395, 2023). "As expected, AEPE decreased hepatic MDA, NO, and PC contents and increased SOD, CAT activities and GSH levels in rats with liver fibrosis." (PMID 34712342, 2021). "Liver fibrosis would gradually result in a reduction in the antioxidant contents (thiols, SOD, and catalase) and an increase in oxidative stress." (PMID 32395205, 2020). "The treatment with atorvastatin ameliorated liver fibrosis in the BDL+At group by the down-regulation of Rac1-GTP, Rac1, and NOX1, as well as the elevation of antioxidant molecules (thiols, SOD, and catalase)." (PMID 32395205, 2020). "Rutin treatment attenuates the reduction of catalase, Cu/Zn-SOD, and GSH in the rat BDL model via AMPK signaling, thereby ameliorating hepatic fibrosis." (PMID 28977988, 2017). "Treatment by TQ restored liver fibrosis, improved liver function tests and increased the levels of anti-oxidative enzymes (SOD and catalase), while reduced MDA concentration (p<0.05)." (PMID 29299433, 2017). "In model group, CCl4-induced liver fibrosis provoked a significant promotion of liver MDA content and obvious reductions of liver GSH-Px, GSH, CAT and SOD activities compared with normal group." (PMID 26083117, 2015). "In HFD group, Masson’s trichome stain intensity increased 6.8-folds, indicating the onset of liver fibrosis; ROS generation and lipid peroxidation (TBARS) were significantly (p < 0.01) increased, whereas SOD and CAT were decreased by 36.7 % and 49.7 %, respectively." (PMID 40520525, 2025). "FAN administration alleviated the inhibition of the Nrf2 pathway in the liver specimens of rodents with hepatic fibrosis by increasing the Nrf2 expression and its downstream detoxification enzymes’ (HO-1, SOD1, and CAT) protein levels and decreasing the protein level of Keap1." (PMID 40910002, 2025). "Similarly, our current study indicated that antioxidant enzymes, such as SOD, CAT, and GSH, were significantly decreased in mice with TAA-induced liver fibrosis." (PMID 37324954, 2023). "Overexpressed CAT has been demonstrated to ameliorate liver fibrosis by inhibiting HSC activation, but not elicit sufficient attention because of complex operation and undefined mechanism." (PMID 36797395, 2023). "However, during treatment with DPx, all abnormal antioxidant activities of SOD, CAT, and GSH were significantly restored in mice with TAA-induced liver fibrosis mice." (PMID 37324954, 2023). "After inducing liver fibrosis, melatonin restored the redox balance by decreasing the levels of ROS, NADPH oxidase 4 (NOX4), iNOS, and MDA, and by rising the activity of several antioxidant enzymes, and the expression of SOD, CAT, and GSH." (PMID 35404472, 2022). "Previous study reported that catalase, anti-IL-6, or siRNA-IL-6 inhibited the phosphorylation of p38 in Kupffer cells which co-cultured hepatic stellate cell and also blocked TIMP1 upregulation and collagen I accumulation for liver fibrosis." (PMID 33809062, 2021). "In addition, PJ showed antifibrotic activity against NDEA-induced liver fibrosis via increasing SOD, GST, and catalase levels and enhanced the antioxidant enzymes, including SOD, catalase, and the GSH levels in liver, kidney, and testis tissues against lead-induced oxidative stress." (PMID 35392110, 2022). "Also, β-carotene, from other algae D. Saline, exerted its antioxidant through inducing catalase and thioredoxin enzymes that attenuated STZ-induced diabetic neuropathy and elevated the levels of GSH with a decrease in MDA opposing hepatic fibrosis induced by TAA in rats." (PMID 33628797, 2021).
liver fibrosis (continued). "Enhancement of the activities of some antioxidant enzymes such as catalase (CAT), glutathione reductase (GR), glutathione peroxidase (GPx), heme oxygenase 1 (HO-1), and superoxide dismutase (SOD) can inhibit oxidative stress and thereby delay the development of liver fibrosis." (PMID 33029279, 2020). "Furthermore, CAT, BLVRB, NXN, PRDX1, and IDH1 may be candidates for detection of liver fibrosis or therapeutic targets for the treatment of liver fibrosis." (PMID 28830339, 2017). "Furthermore, CAT, BLVRB, NXN, PRDX1, and IDH1 may be candidates for the detection of liver fibrosis or therapeutic targets for the treatment of liver fibrosis." (PMID 28830339, 2017). "This work suggests that TGF-β1 is responsible for the diminished CAT in liver fibrosis, and our designed MnO2@PLGA/Ssb1 nanosystem displays enhanced antifibrotic efficiency through removing excess H2O2 and hypoxic stress, which may be a promising therapeutic approach for liver fibrosis treatment." (PMID 36797395, 2023).